AR (androgen receptor)
Diseases named in the same sentence as AR in open-access papers (continued):
Sharing a sentence is not in itself a finding about the gene and the disease.
tumor (continued). "The result revealed that the tumor immune infiltration was different in AR and ERBB2 expression." (PMID 35069767, 2022). "Besides the numerous AR signaling events in PCa cells, chemotherapy widely exerts its anticancer effect by triggering apoptotic mechanisms of tumour cells." (PMID 35129730, 2022). "Interestingly, there is evidence that two key circRNAs, circHIAT1 and circCDR1AS, play important roles in tumor development by controlling AR and PI3K/AKT signaling pathways, respectively." (PMID 35007362, 2022). "As expected, treatment of castrated male mice bearing the VCaP-CRPC xenografts with enzalutamide (an AR antagonist) showed moderate anti-tumour efficacy; however, treatment with AU-15330 led to potent inhibition of tumour growth, triggering disease regression in more than 20% of animals." (PMID 34937944, 2022). "In women, AR protein expression was higher in the peritumoral area than in the tumor core." (PMID 36361793, 2022). "Thus, inhibition of oncogenic PI3K increases tumor growth by unleashing ER/AR signaling in breast and prostate respectively." (PMID 35774123, 2022). "Moreover, the PSA test indirectly monitors tumor activity through AR signaling, which usually correlates with tumor load." (PMID 35456428, 2022). "Altogether this suggests that AR signalling could be involved in metastasis and recurrence of these tumours." (PMID 35267409, 2022). "It is possible that resistance mechanisms maintaining the AR activity (from maintaining intratumor androgen levels) in the tumor microenvironment may also impair the immune checkpoint blockade." (PMID 36430730, 2022). "Alternatively, biomarkers that capture active AR signalling driving tumorigenesis/tumour maintenance may be necessary to faithfully identify patients most likely to benefit from AR-directed therapy." (PMID 36376977, 2022). "Tumours with low androgen receptor activity or of the PAM50 basal subtype may have a reduced response to apalutamide." (PMID 35091711, 2022). "As testosterone levels and AR expression are important for normal prostatic epithelium development and maintenance, it is unsurprising that human prostate cancer (PC) also adopts this mechanism to induce tumor cell proliferation." (PMID 35163087, 2022). "Therefore, the toxic effect of the loaded AR-siRNA NPs on tumor cells was notably less significant than that of the cytotoxic chemotherapeutic agent DTX NPs." (PMID 35631549, 2022). "Src also acts independently of AR signalling to regulate tumour cell proliferation and mobility." (PMID 35832549, 2022). "Inhibition of c-Myc could be carried by multiple miRNAs, including miR-let-7a which also has a tumor suppression function in PCa cells through downregulating AR expression." (PMID 35456461, 2022). "Since, the genetic background of the tumor may dictate how ERG influences AR activity we propose that the results from patient cohorts may be obfuscated by mixed genetic backgrounds of patient tumor samples." (PMID 36212399, 2022). "Inspired by their critical role in PC treatment and the optimal anti-tumor effects of the combination of chemotherapy and RNA interference, we speculate that the combined therapy of AR siRNA and DTX is likely to have an enhanced therapeutic effect on PC." (PMID 35631549, 2022). "In many cases of triple-negative breast cancer (TNBC), the tumour cells show AR expression." (PMID 35163477, 2022). "We cannot determine whether the post-ADT tumor cells that express these factors are in a transient mode of disappearing, still capable of having AR-activity, or represent pre-existing resistant cells." (PMID 36115838, 2022). "Though data are mixed, the balance of early studies on AR levels in HCC tumors found significantly higher AR protein expression when compared with adjacent normal liver tissues and that increased AR protein expression was correlated with increased tumor recurrence and reduced overall survival." (PMID 36430245, 2022).
tumor (continued). "To improve the accuracy of tumor burden assessment, we are expanding this model to incorporate clinical PSA, testosterone, imaging data, histology data on AR and Cyp17 immunohistochemistry and genomic data on ctDNA, AR amplification and mutations in ctDNA." (PMID 36358643, 2022). "Thus, the AR-dependent and AR-independent pathways would cooperate with each other for the tumor suppressive role of ivermectin." (PMID 36050295, 2022). "GO and KEGG enrichment analyses showed that AR-AF regulates the proliferation, apoptosis, migration and angiogenesis of tumor cells by regulating signaling pathways, including the cAMP signaling pathway and PI3K-Akt signaling pathway, thereby playing a role in treating GC." (PMID 35672352, 2022). "Therefore, new therapeutic strategies to effectively target the AR signalling in tumours resistant to AR antagonists are urgently needed." (PMID 35589670, 2022). "Therefore, the activity of PARP is increased, and this latter phenomenon leads to the tumor-cell survival and the modulation of AR axis activity." (PMID 35205654, 2022). "However, AR protein expression in tumors resected from patients was higher in the enhancing tumor region and in the peritumoral area than in the tumor core." (PMID 36361793, 2022). "PCa could exert a regulating activity on glycolysis based on androgen receptor signaling, thereby promoting tumor metabolism and growth." (PMID 36246902, 2022). "pointed out that FV-429 could exerted significant tumor-suppressive effect based on glycolysis inhibition and apoptosis by downregulating the AR-AKT-HK2 signaling axis." (PMID 36246902, 2022). "The efficacy of NK cell killing of BCa cells was measured with MTT to test whether the tumor cell survival probability was reduced and/or enhanced following changes in AR expression and/or activity." (PMID 35915245, 2022). "The expression of AR within macrophages in tumors can potentially promote the growth of tumors and help increase the ki67 expression level, resulting in enhanced tumor invasive properties, suggesting that androgens can potentially improve the ability of macrophages to promote BRCA progression." (PMID 36450882, 2022). "Notably, with repeated exposure to intensive AR-directed therapies, resistance mechanisms continue to converge upon the AR gene body and upstream enhancer, selecting for tumor populations with a greater number of AR copies." (PMID 36439451, 2022). "In the case for PCa treatment however, an intrinsic problem with ADT is that the tumor epithelial cells are the desired targets, but the stroma will also be targeted, which will induce a more lethal microenvironment since AR in stroma is required for a healthy phenotype." (PMID 36115838, 2022). "In this paper, we demonstrate that knocking down AR expression and/or administering antiandrogens can substantially decrease PD-L1 expression in BCa cells, consequently enhancing the efficacy of NK cell killing of tumor cells." (PMID 35915245, 2022). "In vitro studies have confirmed that first generation HSP90 inhibitors (tanespimycin and alvespimycin) and second generation ones (onalespib), inhibit tumor cell growth and induce the degradation of client proteins, including AR-FL, AKT and GR (glucocorticoid receptor)." (PMID 35055079, 2022). "The AR+ group consisted only of tumor samples since no AR mutation was detected in the control group." (PMID 35053623, 2022). "The expression of AR would allow for individualised treatment based on tumour biology." (PMID 36405944, 2022).
tumor (continued). "- Platinum-based chemotherapy may have anti-tumor activity.- Patients who had prior androgen receptor-targeted agent(s) ± chemotherapy should consider olaparib or other PARPi." (PMID 35924163, 2022). "An alternative approach to AR pathway inhibition is to reduce the receptor in tumor cells by its degradation via the ubiquitin-proteasomal pathway, which can be initiated by a small-molecule SARD (Specific AR Degrader) or AR-selective PROTAC (proteolysis-targeting chimera)." (PMID 35205640, 2022). "In 75-80% of patients, sustained AR signaling drives ongoing tumor growth in mCRPC." (PMID 36439451, 2022). "Additionally, single-cell sequencing analyses discovered that AR transcripts are significantly more expressed in circulating tumour cells than in primary tumour cells from TNBC patient-derived xenografts (PDXs)." (PMID 35267409, 2022). "However, recent findings highlight the continuous role of androgen receptor signaling in disease progression in up to 70% of patients whose tumor show different AR aberrations." (PMID 36551557, 2022). "Interestingly, in the face of therapeutic challenge with ARSI, CHD1 loss seems to then allow alternative master transcription factors to dominate, leading to AR-independent mechanisms of tumor growth." (PMID 36212399, 2022). "Taken together, these results demonstrate a promotional role of stromal AR signaling in Gli1-lineage cells to support prostatic epithelial oncogenesis and tumor development, which also provides experimental evidence to use these relevant models for in-depth molecular analyses." (PMID 36323713, 2022). "This hypothesis is based on the observation that the blockade of both AR and PD-L1 reduces tumor growth and that the inhibition of AR improves T-cell function." (PMID 36552000, 2022). "However, only 58% showed AR expression on IHC and apocrine morphology was observed in only 4 tumours (7%)." (PMID 34537861, 2022). "Interestingly, the western blot analyses of key target proteins in the excised tumors reveal that the level of AR was significantly reduced upon VNPP433-3β treatment in a concentration-dependent manner with a concomitant reduction in tumor volume and weight." (PMID 36078112, 2022). "At the clinical level, tumor cells proliferate and grow independently of the AR signaling pathway." (PMID 35938167, 2022). "The second possible explanation for the association may be due to ER expression acting as a proxy for androgen receptor (AR) expression of which AR expression is positively correlated with ER expression in tumours." (PMID 36209141, 2022). "Taken this information into consideration, we speculate that AR can take advantage of the increased FAM to arrest tumor growth in luminal-type BCa, or to promote tumor progression in TNBC." (PMID 35568821, 2022). "Moreover, ATF4 overexpression inhibited tumor proliferation and AR expression both in vitro and in vivo." (PMID 35013318, 2022). "In women, higher AR expression was observed in the peritumoral area than in the tumor core." (PMID 36361793, 2022). "Patients were screened using a backward regression, with age, baseline T–stage, baseline N–stage, histological grade, CNB ER, PR, HER–2, Ki67, AR, AR/ER, AR/PR levels, residual tumor TN stage, residual tumor ER, PR, HER, Ki67, and ΔKi67 as the factors initially included." (PMID 36556209, 2022). "Plasma tumour DNA (ptDNA) has been recently demonstrated as a potential early noninvasive biomarker in patients affected with metastatic castration‐resistant prostate cancer receiving androgen receptor signalling inhibitors." (PMID 34657387, 2022). "Moreover, ablation of the androgen–AR axis rewires the tumor microenvironment to favor effector T cell differentiation and potentiates the efficacy of anti-PD-1 immune checkpoint blockade." (PMID 36273184, 2022). "In addition, we present promising efficacy data using an experimental AR-targeted antisense oligonucleotide (ASO) that significantly delayed tumor growth by suppressing AR expression." (PMID 35650195, 2022).
tumor (continued). "Here, we found that targeting AR could enhance natural killer (NK) cell tumor-killing efficacy by decreasing PD-L1 expression." (PMID 35915245, 2022). "At 2 months, tumor growth began to accelerate in the enzalutamide-treated mice, whereas growth suppression continued in the mice treated with either 25 or 50 mg/kg of the AR-ASO (p < 0.0001)." (PMID 35650195, 2022). "ERG expands AR attachment and transcriptional activity, thus, promoting tumor progression." (PMID 35682963, 2022). "AR activity was also lower in the basal than luminal tumours." (PMID 35091711, 2022). "The authors observed that DHT activated in vitro the AR downstream signaling, down-regulating miR-30a and preventing the inhibition it may exert on cell proliferation as tumor suppressor." (PMID 36111296, 2022). "Long-term ADT can induce upregulation of the enzyme required for the synthesis of androgen in PCa cells, and use its own enzyme system to synthesize androgen, so as to promote the reproliferation and metastasis of tumor cells and continue to activate AR signaling." (PMID 36591491, 2022). "An exploratory analysis of androgen receptor splice variants (ARV7/ARFL) Prostate Specific Antigen (PSA) and Prostate Specific Membrane Antigen (PSMA) expression on Circulating Tumor Cells (CTCs) detected in a preliminary cohort of 31 out of 42 patients was presented at ASCO GU 2021." (PMID 35763249, 2022). "Moreover, we also found a reduction in AR activation in C4-2B cells (p = 0.017) confirming the “indirect” anti-tumor AR-dependent effect of abiraterone mediated by osteoblasts." (PMID 36140255, 2022). "The current study indicated that AR might play roles differently in different pathophysiological conditions such as hypoxia, which influences the tumor microenvironment including tumor cells as well as stromal, endothelial, and immune cells." (PMID 36397101, 2022). "Nodal involvement, males, large tumour, androgen receptor (AR) negativity worsened survival." (PMID 35369277, 2022). "For patient 1, 72% of the 287 epithelial-containing spots with attributed non-responding tumor factors were associated with sAR(−), while 15% were associated with sAR(+) (the remaining spots contained a mixture of AR positive and AR negative cells)." (PMID 36115838, 2022). "In this review, we aimed to highlight WHAT is AR, describing its structure and functions, WHAT to test and HOW to detect AR, WHERE AR should be tested (on primary tumor or metastasis) and WHY studying this fascinating hormone receptor, exploring and debating on its prognostic and predictive role." (PMID 36111296, 2022). "More importantly, they showed that A-485 could inhibit tumor growth in vivo, using an AR-positive, patient-derived castration-resistant xenograft model, making it a promising candidate for clinical trials." (PMID 36060957, 2022). "As controlling the expression level, intracellular localisation and transcriptional activity of TFE3 fusion protein are critical steps for tumour progression of Xp11.2 tRCC, we first investigated the effect of AR on the expression level of wild‐type TFE3 and TFE3 fusions." (PMID 35452181, 2022). "Previous studies on AR in BCa have identified roles in tumor proliferation, progression, and metastasis, and AR inhibitors and the degradation enhancer ASC-J9® could be viable options for BCa therapy." (PMID 35915245, 2022). "Upon androgen stimulation, these cells proliferate, suggesting that these AR-low cells may promote tumor repopulation after ADT." (PMID 35909568, 2022). "Prx1 acts as a tumor suppressor that inhibits tumorigenesis and promotes tumor cell death by interacting with c-Myc and as an oncogene that inhibits tumor cell death by interacting with nuclear factor kappa B (NF-κB) and the androgen receptor (AR)." (PMID 36360274, 2022). "At the same time, tumor conditions (hypoxia and insufficient nutrient supply) may be factors with a significant impact on AR mRNA expression in GBM." (PMID 36361793, 2022).
tumor (continued). "However, the fundamental mechanisms by which the AR, a steroid hormone receptor, functions as a tumor promoter to initiate prostatic oncogenesis and promote tumor progression still remains elusive." (PMID 35902588, 2022). "Nonetheless, tumor cells eventually become resistant due to AR signaling reactivation." (PMID 35686097, 2022). "Targeting the AR signaling pathway may impact or remodel the tumor immune microenvironment to prevent tumor cells from escaping immunosurveillance, better suppress tumor progression and improve patient survival." (PMID 35915245, 2022). "The Au nanoparticle could efficiently accumulate in the tumor site and prolong the half‐life of the AR pep‐PROTAC peptide." (PMID 35971165, 2022). "For example, when the same AR+ PC cell line was implanted in the prostate and in the bone, tumor response to castration therapy was prominent in the prostate but largely absent in the bone, pointing out the importance of site-specific microenvironments for therapy response." (PMID 36358614, 2022). "Increasing evidence demonstrates that ER and AR are involved in tumor initiation and progression." (PMID 35517428, 2022). "Berberine inhibited tumor growth by reducing AR expression in nude mice bearing LNCaP xenografts." (PMID 36139145, 2022). "Indeed, whereas AR+/PSA+ tumor cells form the main cell population in untreated androgen-sensitive tumors, enrichment of AR-/lo and PSA-/lo cells was found in untreated higher grades of the disease and in CRPC." (PMID 35875084, 2022). "Most castration-resistant prostate cancers (CRPCs) rely on AR signaling due to several adaptive tumor responses that facilitate ligand availability and AR activation, foster the emergence of ligand-independent forms of AR activation, or have acquired broader ligand sensitivity." (PMID 36143113, 2022). "Recent evidence suggests that the androgen receptor (AR) can promote tumor progression in DSRCTs." (PMID 35650195, 2022). "Moreover, the protein levels of LRP5, LRP6, TCF-4, and LEF1 in the tumor were also significantly down-regulated by AR decoction or oxaliplatin treatment in xenograft mice." (PMID 34991661, 2022). "However, the persistence of androgen receptor (AR) signalling axis activity, especially the production of androgens in tumours, during systemic castration undermines the therapeutic efficacy of ADT." (PMID 36376959, 2022). "Furthermore, BA inhibited angiogenesis and tumor growth by decreasing the expression of AR and cyclin D in TRAMP mice." (PMID 36139145, 2022). "Due to these activities against ERα, patients with an ERα+ve/AR+ve phenotype would have relatively better clinical features, e.g., smaller tumor, and longer survival time indicated by disease-free survival (DFS), overall survival (OS) and recurrence-free survival (RFS)." (PMID 36499670, 2022). "ADT deprives PCa cells of the stimulatory effects of androgen hormones, either by directly reducing circulating androgen levels, or via AR-signalling inhibitors (ARSi) that block the ability of the androgen receptor (AR) to bind its ligand, thereby attenuating AR-dependent tumour growth." (PMID 36733939, 2022). "AR silencing effectively retarded tumor growth in both KUCaP2 AD and CR tumors." (PMID 35365763, 2022). "Together, these findings indicate the overall heterogeneity of the mechanisms of responses to AR-targeted treatments in CRPC leading to tumor inhibition and, therefore, limitations to create a reliable response signature based on treatment-induced transcriptomic alterations." (PMID 35603787, 2022). "In the group consisting of men and women, AR expression varied between the regions of the tumor: AR expression was higher in the enhancing tumor region and in the peritumoral area than in the tumor core, showing a dependence on tumor conditions (hypoxia and insufficient nutrient supply)." (PMID 36361793, 2022).